FABP4 (fatty acid binding protein 4)
Diseases named in the same sentence as FABP4 in open-access papers (continued):
Sharing a sentence is not in itself a finding about the gene and the disease.
Insulin resistance (continued). "Previous studies have shown associations among plasma FABP4, insulin resistance, metabolic syndrome, diabetes mellitus, greater coronary plaque burden, coronary artery disease, heart failure, and mortality." (PMID 31234795, 2019). "Insulin resistance is linked to increased lipolysis, and secretion of FABP4 into the serum is stimulated by lipolysis." (PMID 30969942, 2019). "In mammals, FABP4 is expressed in adipocytes and macrophages and has been shown to be associated with insulin resistance, atherosclerosis and metaflammation." (PMID 31035349, 2019). "FABP4 is implicated in the development of insulin resistance, atherosclerosis, non-alcoholic fatty liver disease, and obesity." (PMID 30635550, 2019). "Previous studies performed on FABP4-deficient mice indicated that this lipid chaperone made important effects on metabolic syndrome, insulin resistance and atherogenesis." (PMID 30969942, 2019). "This reflects that the level of FABP4 itself is associated with glycolipid metabolism, insulin resistance and other metabolic factors." (PMID 29394285, 2018). "Elevated circulating FABP4 level is associated with obesity, insulin resistance, type 2 diabetes mellitus, dyslipidemia, hypertension, renal dysfunction, cardiac dysfunction, atherosclerosis and cardiovascular events." (PMID 28303004, 2017). "Accordingly, the results of our study show the possibility that, while FABP4 is important for the pathophysiology of insulin resistance, it is likely to be associated with the insulin secretion in T2DM." (PMID 28654680, 2017). "In humans, increased plasma concentrations of FABP4 have been associated with atherosclerosis, cardiac diastolic dysfunction, hypertension, insulin resistance, and obesity." (PMID 28924246, 2017). "We found that serum FABP4 concentration were associated with insulin resistance and secretion in T2DM." (PMID 28654680, 2017). "It is known that the FABP4 level is associated with obesity, insulin resistance, and atherosclerosis." (PMID 26887419, 2016). "FABP4 has been implicated in several aspects of the metabolic syndrome in mice, including insulin resistance and atherosclerosis." (PMID 26887419, 2016). "While both FABP4 and FABP5 were closely associated with insulin resistance and measures of adiposity, only FABP4 showed a decrease in concentration in response to the 6-month intervention with the FVJC supplement." (PMID 26688725, 2015). "AMPK's inactivation followed by possible increased plasma FFA levels and the up-regulation of FABP4 expression in DDT knockdown adipocytes suggested reduced DDT expression in adipocytes to be associated with insulin resistance." (PMID 22428043, 2012). "Mice where FABP4 expression has been abolished are less susceptible to develop insulin resistance and dislipidemias." (PMID 20540717, 2010). "Studies have shown that dietary intake of propionate in humans can lead to increased postprandial plasma concentrations of glucagon, fatty acid-binding protein 4 (FABP4), and norepinephrine, which may cause insulin resistance and then increase glucose." (PMID 39194508, 2024). "Propionate may cause glycogenolysis, insulin resistance, and hyperglycemia by increasing plasma levels of glucagon, insulin counter-regulatory hormones, and fatty acid-binding protein 4 (FABP4) in both mice and humans." (PMID 37432305, 2023). "Elevated circulating FABP4 concentrations have been associated with insulin resistance in adults." (PMID 37274820, 2023). "FABP4-deficient mice exhibit severe insulin resistance, and NAFLD is known to be associated with an increased risk of other extrahepatic complications, including type 2 diabetes, fatal and non-fatal cardiovascular diseases (CVD), as well as incident chronic kidney diseases (CKD)." (PMID 37740216, 2023). "FABP4-deficient mice show higher body weight with decreased insulin resistance." (PMID 35892532, 2022).
Insulin resistance (continued). "Thus, FABP4 has also been found to be associated with insulin resistance in the survival prognosis of THCA patients." (PMID 36532833, 2022). "In addition, the hepatic expression of FABP4 mRNA was examined, the level of which has been linked to insulin resistance, T2DM, hypertension and cardiac dysfunction." (PMID 34046014, 2021). "Thus, in the current study, a nested case-control design will be used to prospectively investigate the associations of FABP4 levels with insulin resistance and GDM after accounting for lifestyle factors." (PMID 34368366, 2021). "A raised FABP4 value has been associated with diabetes mellitus, development of atherosclerosis, inflammation, and insulin resistance; and the iron accumulation in patients with thalassemia major may induce these conditions." (PMID 34987673, 2021). "Likewise, studies in animal models found that, even being challenged by high-fat diets, FABP4-deficient mice were protected from hyperglycemia, hyperinsulinemia, and insulin resistance." (PMID 34368366, 2021). "Similarly, previous studies also observed the positive association between FABP4 levels at 6, 24-28, or 23-30 weeks of gestation and insulin resistance." (PMID 34368366, 2021). "Fatty acid binding protein 4 (FABP4) has been associated with insulin resistance." (PMID 34621244, 2021). "Furthermore, it is also known that serum FABP4 levels are elevated by insulin resistance and atherosclerosis, which causes DM and hypertension (HT), respectively." (PMID 34117325, 2021). "FABP4 has been implicated in cardiometabolic disease: a SNP which increases FABP4 was found to raise the odds of type II diabetes among adults, potentially through its contribution to higher insulin resistance." (PMID 34226637, 2021). "Elevated FABP4 levels in the first and second trimesters were associated with a higher level of insulin resistance and greater GDM risk, indicating FABP4 might predict women with high risk of developing GDM." (PMID 34368366, 2021). "FABP-4 and leptin are hormonal bioactive molecules secreted by adipose tissue that control energy balance, have been linked to metabolic and inflammatory pathways, and are associated with the development of insulin resistance and atherosclerosis." (PMID 34312731, 2021). "Fatty acid binding protein 4 (FABP4) is a newly described adipocytokine that is released from adipocytes and macrophages and is associated with the development of metabolic syndrome (MetS), insulin resistance, and increased inflammation." (PMID 31651119, 2019). "Circulating FABP4 is associated with lipolysis and may aggravate insulin resistance compared to normal physiological insulin resistance during pregnancy." (PMID 30857223, 2019). "Previous studies had suggested that different variables recorded on admission were associated with poor outcome in stroke patients, for example insulin resistance, vitamin D deficiency or 25-hydroxyvitamin D, fatty acid-binding protein 4, C-reactive protein, and homocysteine." (PMID 30038059, 2018). "Additionally, clinical findings support that increased FABP4 serum levels are associated with insulin resistance and secretion in patients with type 2 diabetes mellitus, suggesting that FABP4 plays an important role in peripheral glucose homeostasis (also linked to the onset of AD)." (PMID 35457171, 2022). "Besides, it is well described role as a lipid chaperone and adiposity biomarker, FABP-4 is associated with features of the metabolic syndrome, insulin resistance, atherosclerosis, and low-grade inflammation and has been proposed as a biomarker for cardiovascular disease and heart failure." (PMID 33535425, 2021). "Therefore, FABP4 may contribute to classical risk factors including insulin resistance and/or metabolic syndrome and might be a kind of “master regulatory factor” of metabolic risk factors." (PMID 33597568, 2021). "Moreover, FABP4 is an independent risk factor for increased insulin resistance in pregnancy." (PMID 34769010, 2021).
Insulin resistance (continued). "However, it is still unknown whether association of elevated circulating FABP4 level with insulin resistance is a result of direct physiological effects of FABP4 as a bioactive molecule in vivo." (PMID 24278421, 2013). "Silencing of fatty acid binding protein 4 and 12/15-lipoxygenase selectively and specifically in adipose tissue prevents the development of insulin resistance." (PMID 41668130, 2026). "Circulating FABP‐4 is involved in lipid modulation, metabolic regulation (including insulin resistance), and inflammation." (PMID 40857027, 2026). "Animal model studies have indicated that FABP4 levels are essential for insulin resistance and an enhanced plasma lipid profile, thereby promoting atherosclerotic plaque formation." (PMID 40728998, 2025). "FABP4 is a key factor in insulin resistance, promoting cholesterol accumulation in macrophages and activating IKK-NF-kB and JNK-AP-1 pathways." (PMID 41471323, 2025). "Clinical studies have shown that increased serum FABP4 levels are closely associated with MASLD, insulin resistance, liver fibrosis, and even HCC." (PMID 41035773, 2025). "Given the involvement of FABP4 in lipid pathways and insulin resistance, further studies on how the expression of FABP4 is changed throughout pregnancy can shed light on the development of GDM." (PMID 40128623, 2025). "FABP4 KD restored contractility, while Mfn2 overexpression improved mitochondrial function and alleviated insulin resistance." (PMID 40192565, 2025). "FABP4 knockout mice and other studies have demonstrated its important role in adipogenesis and insulin resistance." (PMID 39627016, 2024). "In a cross-sectional study, the relationship between FABP4, insulin secretion, and insulin resistance in 12 T2DM patients and 18 controls was evaluated." (PMID 38731797, 2024). "Previous studies have indicated that the secretion of FABP4 as an adipokine has the direct capability to trigger the onset of insulin resistance and lipid metabolism." (PMID 39527497, 2024). "FABP4, which is secreted by adipocytes, has well-documented implications for insulin resistance and atherosclerosis, consistently showing elevated levels in persons developing incident CHD." (PMID 38310303, 2024). "In summary, adipokine markers contributing to insulin resistance, such as leptin, chemerin, FABP4, and RBP4, are typically elevated in GDM, whereas those contributing to insulin sensitivity, like adiponectin, are reduced in GDM." (PMID 39519218, 2024). "Treatment with recombinant FABP4 induces insulin resistance in mice, suggesting a role of FABP4 in regulating insulin sensitivity." (PMID 37274820, 2023). "The research on FABP4 inhibitors started when it was reported that knockout animal models of FABP4 naturally developed protective effects against insulin resistance and other events, such as metabolic syndrome and atherosclerosis." (PMID 36985701, 2023). "Glucose stimulates FABP4 expression in trophoblast cells, which enhances lipolysis and exacerbates pregnant insulin resistance (IR), especially in the first and second trimesters." (PMID 37628833, 2023). "They include the fatty acid binding protein 4 (FABP4), retinol-binding protein 4 (RBP4), and adiponectin, which have been associated with liver steatosis and insulin resistance." (PMID 38034016, 2023). "As an adipokine, FABP4 has been reported to stimulate hepatic glucose production and augment insulin secretion, contributing to insulin resistance and hyperglycemia." (PMID 35909571, 2022). "Many previous studies have shown that FABP4 is relevant to the development of metabolic diseases (e.g., atherosclerosis, insulin resistance, T2D), cardiovascular disease, asthma, and cancer." (PMID 36060264, 2022). "Increased FABP4 induces lipolysis in the adipocytes and contributes to insulin resistance and inflammation." (PMID 36429582, 2022).
Insulin resistance (continued). "Pharmacological inhibition or genetic ablation of FABP4 has been shown to be effective in alleviating insulin resistance, atherosclerosis, and nonalcoholic fatty liver disease." (PMID 33690220, 2021). "We further found that FABP4 levels in the first trimester and the second trimester were positively correlated with insulin resistance in the second trimester." (PMID 34368366, 2021). "Fatty‐acid‐binding protein 4 (FABP4) is mainly expressed in adipocytes and macrophages and plays important roles in the development of insulin resistance and inflammation." (PMID 33314576, 2021). "The study is aimed at examining the effects of fatty acid-binding protein 4 (FABP4) on insulin resistance and gestational diabetes mellitus (GDM)." (PMID 34368366, 2021). "FABP4 has been shown to play a significant role in the development of insulin resistance, type 2 diabetes mellitus and atherosclerosis through its action at the interface of metabolic and inflammatory pathways in adipocytes and macrophages." (PMID 33597568, 2021). "It is well known that adipocyte hypertrophy and increased adiponectin secretion in the adipose tissue are responsible for insulin resistance, consistent with the increased circulating FABP4 and insulin levels in Crtc1–/– mice observed in our study." (PMID 33912553, 2021). "Fatty acid-binding protein 4 (FABP-4), a novel adipokine, is found to induce insulin resistance and type 2 DM." (PMID 34217172, 2021). "Several FABP4 inhibitors have been shown to be effective in alleviating chronic inflammatory disorders, including insulin resistance, atherosclerosis, nonalcoholic fatty liver disease, and osteoarthritis." (PMID 33690220, 2021). "Plasma levels of FABP4 are markedly increased in obese subjects compared to normal weight controls and circulating FABP4 levels positively correlate with increased waist circumference, dyslipidemia, and insulin resistance." (PMID 32856199, 2020). "Fatty acid–binding protein 4 (FABP4) was highly expressed in adipocytes and macrophages, and played crucial roles in insulin resistance and atherosclerosis." (PMID 33101287, 2020). "FABP4 is a chaperone that transports fatty acids, and it is involved in insulin resistance, inflammation, and foam cell formation." (PMID 32121518, 2020). "Circulating FABP4 induces insulin resistance, which is an independent biomarker of proliferative retinopathy." (PMID 30857223, 2019). "There is ample scientific evidence to suggest a link between the fatty acid-binding protein 4 (FABP4) and insulin resistance, gestational (GDM), and type 2 (T2DM) diabetes mellitus." (PMID 30857223, 2019). "FABP4 has been shown to play a crucial role in insulin resistance, type 2 diabetes, and atherosclerosis." (PMID 30575815, 2019). "The plasma FABP4 levels have been reported to be upregulated in obese patients and positively correlate with BMI and insulin resistance." (PMID 31736755, 2019). "The human white adipocytes express two FABPs: adipocyte Protein 2 (aP2) and FABP4; this last is secreted from adipocytes and acts as an adipokine for the development of insulin resistance and atherosclerosis." (PMID 31357412, 2019). "Some scholars believed that there is a potential link between FABP4 and hyperlipidemia, hyperinsulinemia, and insulin resistance, which indirectly affects cancer cells by affecting these factors." (PMID 31651326, 2019). "Both increase in serum FABP4 level and the presence of hypothyroidism have roles in the development of MetS, dyslipidemia, insulin resistance, and CVD." (PMID 31651119, 2019). "Of the more recently discovered pro-inflammatory adipokines, the insulin resistance-inducing FABP4 is an interesting candidate, which seems to be involved in the pathophysiology of GDM." (PMID 30513800, 2018). "We also investigated the influence of the state of glucolipid metabolism and insulin resistance on FABP4 and the development of GH/PE." (PMID 29394285, 2018).
Insulin resistance (continued). "FABP4 regulates metabolic and inflammatory pathways, and its down‐regulation can alleviate insulin resistance and atherosclerosis." (PMID 29160030, 2018). "Both FABP4 and FABP5 are secreted from cells, and their circulating levels are associated with insulin resistance and atherosclerosis." (PMID 28303004, 2017). "We previously demonstrated that inhibition of FABP4 in cells would be a novel therapeutic strategy against insulin resistance, diabetes mellitus and atherosclerosis." (PMID 28303004, 2017). "Recent work has demonstrated that macrophage FABP4 integrates inflammatory and lipid metabolic responses, thereby contributing to the development of insulin resistance and atherosclerosis." (PMID 28331434, 2017). "Accordingly, the measurement of FABP4 concentration is useful for evaluating insulin resistance in skeletal muscle if FABP4 significantly correlates to GDR, and is a predictive marker of the progression of T2DM and non-DM people." (PMID 28654680, 2017). "There are a large number of studies that assessed the correlation with FABP4 and insulin resistance." (PMID 28654680, 2017). "FABP4 is considered as an important substance concerning insulin resistance in T2DM, and for the release of compensatory insulin secretion." (PMID 28654680, 2017). "Assessing this result, we assume that FABP4 enhances the process that β cells compensate insulin secretion against the insulin resistance in patients with T2DM." (PMID 28654680, 2017). "Previous studies using FABP4- and FABP5-deficient mice demonstrated that both FABP4 and FABP5 play significant roles in the development of insulin resistance, diabetes mellitus and atherosclerosis." (PMID 28303004, 2017). "We previously showed that inhibition of FABP4 in the cell would be a novel therapeutic strategy against insulin resistance, diabetes mellitus and atherosclerosis." (PMID 27936164, 2016). "Previous studies using in vitro and in vivo experiments showed that FABP4 acts as an adipokine leading to the development of hepatic insulin resistance through increased hepatic glucose production and atherosclerosis." (PMID 27124282, 2016). "Circulating FABP4 has been demonstrated to participate in the pathogenesis of atherosclerosis and to be closely related to insulin resistance, Type 2 diabetes and the metabolic syndrome." (PMID 26823558, 2016). "Secreted FABP4 as a novel adipokine leads to insulin resistance via increased hepatic glucose production (HGP)." (PMID 27124282, 2016). "Compared to patients with decreased FABP4 level by canagliflozin (33.3%), patients with increased FABP4 (66.7%) had significantly smaller improvement of insulin resistance assessed by change in HOMA-R." (PMID 27124282, 2016). "Accumulating data provide evidence that FABP4 plays a role in the metabolic syndrome, insulin resistance and atherosclerosis." (PMID 26823558, 2016). "The association of cardiovascular events and serum FABP4 level has been explained by a significant role of FABP4 in insulin resistance and atherosclerosis." (PMID 27124282, 2016). "Other important mechanisms included presence of insulin resistance, excessive visceral adipose tissue, activity of circulating dipeptidyl peptidase-4 and fatty acid-binding protein-4." (PMID 26369690, 2015). "FABP4, also known as adipocyte FABP (A-FABP) or aP2, is expressed in both adipocytes and macrophages and plays important roles in the development of insulin resistance and atherosclerosis." (PMID 25506691, 2014). "Emerging evidence indicates that FABP4 acts at the integration between metabolic and inflammatory pathways and plays an important role in the development of insulin resistance and atherosclerosis." (PMID 25142635, 2014). "While several studies have examined the effects of FABP4 expression on adiposity, insulin resistance, metabolic syndrome, and type 2 diabetes, there are only limited data available regard in type 1 diabetes mellitus." (PMID 24593955, 2014).